KRAS (KRas proto-oncogene, GTPase)
Diseases named in the same sentence as KRAS in open-access papers (continued):
Sharing a sentence is not in itself a finding about the gene and the disease.
cancer (continued). "Together, our findings unveil a complex web of molecular alterations that may impact the therapeutic susceptibility of KRAS and EGFR-mutant non-Sq NSCLC across different ancestry groups and consequently may contribute to molecular underpinnings of cancer disparities." (PMID 39033203, 2024). "However, our further analyses do not support that SG are formed in KRAS-driven cancers." (PMID 39390257, 2024). "However, because GTP binds KRAS protein with picomolar affinity and given the physiological roles of GTP in normal cells, the metabolic pathways by which GTP production is limited to inhibit cancer progression need to be better understood for the design of effective drugs." (PMID 37937641, 2023). "However, it is crucial to note that this approach may not universally apply to all KRAS-driven cancers." (PMID 38111008, 2023). "While KRAS dependency may not be on a linear scale, we have defined three clusters of dependency that may help characterize and discriminate differences across various cancer subtypes and even genotypes." (PMID 37141389, 2023). "In summary, therefore, by shedding more light on the role of the ISR in mutant KRAS signaling and lung tumorigenesis, our work strongly suggests that innovative therapeutic approaches using ISR inhibitors may be valuable for the treatment of one of the deadliest forms of mutant KRAS-driven cancer." (PMID 34330898, 2021). "Therefore, combining KRAS inhibition with immune checkpoint blockade has a strong biological rationale and could open the way to therapeutic options, reversing the innately immunoresistant phenotype of some RAS mutant cancers." (PMID 33777798, 2021). "Up to date, designed KRAS-targeting molecules do not show clear benefits in patient overall survival (POS) so pharmacological modulation of aberrant tricarboxylic acid (TCA) cycle in hypoxic cancer has been proposed as a metabolic vulnerability of KRAS-driven tumors." (PMID 33664850, 2021). "However, there is no direct evidence that KRAS regulates ATP production in cancer." (PMID 33537098, 2021). "Importantly, this K-Ras-directed activity was also observed with the Hsp90 ATP-pocket inhibitor 17-AAG (17-N-allyloamino-17-demethoxygeldanamycin), suggesting that Hsp90 inhibitors may have, in general, interesting potential in KRAS mutant cancers." (PMID 34199986, 2021). "However, current models of oncogene addiction are notable for their limitations, as many KRAS mutant cell lines are not strictly dependent on continued KRAS expression, and KRAS mutant cancers have been classified into discrete molecular subtypes based on the degree of KRAS addiction." (PMID 33674596, 2021). "Therefore, the combination of SHP2 and MAPK inhibitors for treating KRAS or BRAF mutant cancers may not benefit all patients when FGFRs are involved in the feedback activation." (PMID 32076487, 2020). "Using the CRISPR/Cas9 system, we generated isogenic cell lines with EGFR/KRAS co-mutations from the KRAS-mutated A549 cell line, and demonstrated that these co-mutated cell lines were more susceptible to EGFR-TKIs, but not to conventional anti-cancer drugs, than parental cells." (PMID 32130260, 2020). "The reduction of elevated RAS protein levels caused by APC and KRAS mutations might be an ideal therapeutic strategy that can target both CSCs and non-CSC cancer cells that have the potential to dedifferentiate into CSCs, without causing toxicity to healthy stem cells." (PMID 31362761, 2019).
cancer (continued). "Moreover, with MYC expression data obtained before rather than during treatment, KRAS WT but not KRAS mutant cancer cells can be classified in terms of whether they would be sensitive or resistant to cytotoxic drugs." (PMID 28152508, 2017). "It’s tempting to speculate that the reason why KRAS is the most important isoform during development and in cancer is because a high KRAS expression level versus the other Ras isoforms means that Ras networks more often than not initiated by KRAS and therefore tuned to respond to this isoform." (PMID 28117393, 2017). "However, the role of stk33 in KRAS-dependent cancer cells remains disputed because other research groups were not able to find a correlation between the knockdown or inhibition of stk33 and KRAS-dependent cancer cell survival, neither using RNAi nor small molecule inhibitors." (PMID 26199010, 2015). "Finally, we also reviewed PIK3CA, CTNNB1, and ARID1A, as well as KRAS and BRAF, for somatic mutations in these genes have been reported to occur in EOC subtypes and corresponding cell lines most often representing other non-HGS subtype cancers." (PMID 26622941, 2015). "Finally, KRAS-G13D induced EGFR expression, senescence, and a distinct pattern of transcriptional changes that may help explain the improved response of patients with G13D-positive cancers to anti-EGFR therapies." (PMID 25705018, 2015). "However, unlike type I cancers (such as clear cell or low-grade endometrioid cancers, which exhibit mutations in PTEN and PIK3CA), the pathway alterations in HGSCs are characterized by deletions (PTEN) and amplifications (PIK3CA, KRAS, and AKT1/2)." (PMID 27231561, 2015). "Moreover, among the 263 paired cancer tissues with wild type KRAS, 249 were negative through WEnCA." (PMID 24884535, 2014). "Additionally, while the described studies specifically identify a requirement for Cdc42 in HRasV12-driven transformation, how Cdc42 might affect transformation resulting from the activation of other Ras proteins (i.e. KRAS and NRAS) commonly activated in human cancers remains to be explored." (PMID 22719838, 2012). "Oncogene activation is a sine qua non of cancer, and thus the LSCC cells that we have examined will certainly express at least one and likely several aberrant oncogenes, although as is typical of SCCHN, none of these cell lines harbour mutations in KRAS (our unpublished data)." (PMID 20588277, 2010). "Concerning ENO2, literature reports indicated upregulation in cancer rather than downregulation, as it occurred in our mutant transfected cells, but additional studies are needed to find any specific correlation of this subunit of the enolase in CRC and KRAS/BRAF mutations." (PMID 19087308, 2008). "Moreover, the non-uniform KRAS G12C nucleotide exchange rates within cancer cells may generate varied drug responses, whereas uniform silencing of KRAS via siRNA consistently induces a quiescent state, underscoring the role of target dynamics in shaping treatment heterogeneity." (PMID 41541668, 2026). "Additionally, analysis of datasets from the Cancer Dependency Map (DepMap) portal did not reveal a substantial correlation between KRAS expression and KEAP1 expression, indicating that NRF2 activation, in the context of KRAS mutations, does not occur via the conventional KEAP1-dependent pathway." (PMID 40091835, 2025). "In addition, we provide a molecular basis for how Hh signals induce re-expression of KRAS in cells treated with a KRASG12C inhibitor, implying that combined treatment of KRASG12C inhibitors and Hh signal inhibitors may overcome acquired resistance in cancer patients harboring KRASG12C." (PMID 38225225, 2024).
cancer (continued). "In Xena, however, ATG10 was found to be non-significantly overexpressed in cancer patients, although KRAS-mut expressed ATG10 more than KRAS-WT patients." (PMID 39057088, 2024). "With no known anti-cancer gene in the RAS pathway, the interaction between miR-21 and KRAS highlights its significance as a target for therapeutic intervention and cancer prognosis." (PMID 38891080, 2024). "B-RAF mutant cancer cell lines have been shown, as expected, to be highly responsive to MEK inhibition but not AKT inhibition, whereas KRAS-mutant cell lines show almost equal sensitivity to both MEK and AKT inhibition." (PMID 39372214, 2024). "However, we did not detect any KRAS protein signal in the immunoprecipitated samples of Flag-hnRNPA2B1, implying that hnRNPA2B1 might carry distinct functional missions in different cancer species." (PMID 37716979, 2023). "Together, these results indicated that cancer cell lines used β-oxidation and glutamine rather than glucose as the main source of fuel for the TCA cycle, independently of KRAS status." (PMID 35681624, 2022). "EGFR-mut and KRAS-mut cancers, but not NEK cancers, had both stabilizing and directional selection among genes of the membrane protease family TMPRSS." (PMID 36612014, 2022). "Preclinical studies showed FTIs failed to inhibit KRAS and NRAS function due to alternative membrane-binding mechanisms; therefore, only HRAS-mutant cancer cells were sensitive to FTIs." (PMID 36012655, 2022). "In KRAS-mut and NEK cancers no genes of the COL family were conserved, while 9 and 11 genes were highly mutated, respectively." (PMID 36612014, 2022). "Recently, several studies have identified that somatic driver mutations that are thought to contribute to EC pathogenesis, including PIK3CA, KRAS and PIK3R1, can exist in normal uteri without cancer." (PMID 36424602, 2022). "Src inhibitor dasatinib synergizes with trametinib to induce cell cycle arrest and apoptosis by downregulating TAZ in KRAS-mutant cancer cells, but not in wild type KRAS or EGFR mutant cancer cells." (PMID 35966590, 2022). "Although knocking down RADIL did not reveal a mutant KRAS-specific toxicity, a significant decrease in cell viability upon RADIL knockdown suggested that RADIL is important for cancer cells in general." (PMID 35839996, 2022). "Unlike KRAS and NRAS, HRAS can only be prenylated by FTase; therefore, FTIs can still be useful for the treatment of HRAS-mutant cancers." (PMID 34200676, 2021). "In OncoKB but not the Cancer Gene Census, amplifications of CDK4 and BRAF are annotated as oncogenic whereas amplification of KRAS is likely oncogenic." (PMID 34313788, 2021). "Conversely, KRAS induced autophagy via the noncanonical KRAS–PI3K–AKT1–GLI3–VMP1 axis to enhance tumorigenesis and cancer progression in KRAS-driven tumors." (PMID 34638233, 2021). "In experiments on human cancer cell lines, the lack of TBK1 induced apoptosis which was specifically dependent on oncogenic KRAS expression." (PMID 34944712, 2021). "Also, such a finding should not be considered proof that this gene plays a role in cancer prevention unless it was validated that a Cre-mediated conditional knockout of the target gene does not lead to a negative selection of pancreatic progenitors and their descendants with mutant KRAS." (PMID 34491463, 2021). "Intriguingly, rAF-IL12 did not downregulate the expression of KRAS and MAPK1 in CT26 cancer cell line as their expression level was similar to the untreated and AF2240-i." (PMID 32612457, 2020).
cancer (continued). "Even though RAS genes were the first oncogenes to be discovered, no targeted therapy for KRAS, NRAS, or HRAS mutant cancers has made its way to clinical application." (PMID 32612138, 2020). "K13 and K19 DARPins selectively inhibit the PI3K/AKT pathway in the KRAS mutant HCT116 cell line, but not in the other cancer cell lines, while K27 inhibits this pathway in HCT116 and MCF-7 cells." (PMID 31197133, 2019). "AZD4785 downregulates both WT and mutant KRAS protein, but only inhibits the downstream MAPK and PI3K signalling pathways of mutant KRAS expressing cells and not of KRASWT expressing cancer cells." (PMID 31197133, 2019). "Second, when fatty acid-free media were supplemented with fatty acid-free albumin-complexed palmitate in order to facilitate its uptake by cancer cells, FASNlox/lox-PyMT, FASNlox/lox-HER2, or FASNlox/lox-KRAS MEFs did not form colonies in soft agar." (PMID 31676791, 2019). "The discriminant isoforms in the invasive phenotype (MITF–) were enriched for multiple cancer hallmarks, whereas the proliferative phenotype (MITF+) presented enrichment only for activation of KRAS signaling, which does not appear in the invasive phenotype." (PMID 27535130, 2016). "Although intensive studies have been conducted on K-Ras protein structure, biochemistry, signaling, and biology, effective treatments for KRAS-mutant cancers have not yet been developed." (PMID 27793187, 2016). "While critical for transducing signals emanating from oncogenes such as KRAS and other receptor tyrosine kinases including ErbB-family receptors, the pathway is not known to play a critical role in HER2-amplified cancers." (PMID 27035903, 2016). "Roles of KRAS and BRAF in other cancers are not discussed here, but have recently been reviewed elsewhere." (PMID 26299805, 2015). "Notch signaling is active in “tumor propagating”, i.e., cancer stem cells in NSCLC models, and Notch3, in particular, is nonredundant in KRAS-driven tumors." (PMID 24722523, 2014). "While the transcriptional regulation of cytokine gene expression in KRAS mutant cancers is complex, together our data suggest that in certain genetic contexts, electrophile-based NRF2 induction, and not KRAS inhibition per se, is specifically required for NISP gene induction." (PMID 40890297, 2025). "In addition, we demonstrate that KRASG12C inhibitors decreased Aurora kinase A (AURKA) levels in cancer cells, and inhibition of AURKA using siRNA or inhibitors led to increased expression levels of GLI-1 and KRAS even in the absence of KRAS inhibitor." (PMID 38225225, 2024). "For example, we hypothesize that we can use the KRAS-sensing circuit to selectively express immunostimulatory signals (such as IL-12, surface T-cell engagers, and anti-PD1) to mark cancer cells for T cell-mediated destruction without affecting normal cells." (PMID 35177637, 2022). "Notably, the synergy occurred across a wide dose range of AZD4547 and BI2536 in KRAS‐mutant lung and pancreatic (H358, H441, A549, and MIAPaCa‐2), but not in KRAS‐mutant colon (SW620, DLD‐1) nor KRAS‐WT lung (EBC‐1, H1993) cancer cells." (PMID 34369083, 2021). "However, once converted into a KRAS degrader, it only inhibited mutant KRAS cancer cells, while the pan-RAS degrader showed no specificity for any RAS isoform mutant protein like the parental binders iDAb RAS and DP KRAS." (PMID 32591521, 2020).
cancer (continued). "In addition, we found that matrine impairs the growth of KRAS‐mutant PDAC, but not KRAS‐wt PDAC; therefore, these observations indicate that matrine can be an appropriate therapeutic reagent for KRAS‐driven cancers with high basal levels of autophagy." (PMID 29791786, 2018). "Interestingly, expression of only LAMB3, and not FAK, is upregulated by KRAS; yet silencing of either FAK or LAMB3 recapitulates miR-1298-induced cell death in KRAS-dependent cancer cells." (PMID 29891810, 2018). "In addition, SB was not able to induce apoptosis in eight human cancer cell lines that harbor wild-type KRas (H661, H2126, H322, H1299, H522, PC9, H4006, and DU145) as compared to those that harbor mutant KRas." (PMID 30514931, 2018). "The products of many of these oncogenes—such as STAT3, KRAS, or MYC—are CCT substrates; hence, each patient whose cancer overexpresses CCT could be treated without the need of molecular subtyping the downstream substrates." (PMID 29299146, 2017). "As these genes besides APC, KRAS and SMAD4 are listed in neither of the cancer Census Genes nor the COSMIC CRC genes, they might be passenger mutations or HGCA-specific mutations that might not play an important role in HGCA progression to CRC." (PMID 28179590, 2017). "This study enrolled a cohort of patients, who had received cetuximab treatment after two or more lines of chemotherapy for KRAS wild-type (exon 2 nonmutant) metastatic CRC, from the databases of Taiwan Cancer Registry (2004–2010) and National Health Insurance (2004–2011)." (PMID 27221731, 2016). "The lack of the genetic complexity found in human regulatory pathways and the lack of interference from wild-type KRAS and other human RAS family isoforms may explain the stronger phenotype observed in yeast compared with the human non-cancer colon cell model." (PMID 26418750, 2015). "Furthermore, our TCR recognized mutant KRAS G12V8–16, but not KRAS WT8–16 peptide, which suggests that our TCR should not recognize normal cells and potentially can be used as an “off-the-shelf” reagent for cancer immunotherapy." (PMID 39846249, 2025). "In this KRAS mutant context, PDHK4 downregulation did not affect the PDH phosphorylation levels (Ser293 or Ser300), suggesting that PDHK4 could play a previously un-appreciated role in mutant KRAS cancer models." (PMID 28692044, 2017). "Considering these observations together with our results, KRAS-mediated activation of the ERK–RSK pathway regulates not only EphA2 protein expression but also the phosphorylation of EphA2, which consequently results in high level expression of pS-EphA2 leading to cancer metastasis." (PMID 26158630, 2015).